USP49 (ubiquitin specific peptidase 49)
Description:
Deubiquitinase that plays a role in several cellular processes including transcriptional regulation, cell cycle progression or innate immunity. Specifically deubiquitinates histone H2B at 'Lys-120' (H2BK120Ub), a specific tag for epigenetic transcriptional activation and acts as a regulator of mRNA splicing. Antagonizes DNA double-strand break-induced ubiquitination of H2AX thereby participating in the maintenance of genome integrity. Plays a role in the negative regulation of cell proliferation through the AKT pathway by deubiquitinating FKBP51, leading to enhanced AKT1 dephosphorylation by PHLPP1. Also regulates the mitotic spindle checkpoint and prevents aneuploidy. Negatively regulates cellular antiviral responses via deconjugating 'Lys-63'-linked ubiquitination of STING1. Significantly enhances the anti-HIV-1 activity of APOBEC3G. Mechanistically, stabilizes APOBEC3G by counteracting HIV-1 Vif-mediated APOBEC3G ubiquitination.
Synonyms: MGC20741
Tractability: PROTAC: ubiquitination databases record sites on it.
Target class: Cysteine protease; Cysteine protease CA clan; Protease; Enzyme; Cysteine protease C19 family
Gene: Protein-coding gene on chromosome 6 (41,789,896 to 41,895,375, reverse strand). Ensembl gene ENSG00000164663.
Subcellular location: Nucleus; Cytoplasm
Pathways (Reactome):
Metabolism of proteins: Ub-specific processing proteases
Gene Ontology:
Molecular function: cysteine-type deubiquitinase activity; cysteine-type endopeptidase activity; histone binding; histone H2B deubiquitinase activity; protein binding; zinc ion binding
Biological process: mRNA splicing, via spliceosome; negative regulation of phosphatidylinositol 3-kinase/protein kinase B signal transduction; protein deubiquitination; chromatin remodeling
Cellular component: cytoplasm; nucleus; nucleoplasm
Genetic constraint (gnomAD): Loss-of-function variants: 23 observed, 56.62 expected, observed/expected ratio (o/e) 0.41, 90% interval 0.29 to 0.58. The upper end of that interval is the gene's LOEUF score, 0.58, which puts it in group 2 of 6, group 1 being the genes least tolerant of losing a copy. Missense variants: 679 observed, 849.26 expected, observed/expected ratio (o/e) 0.8, 90% interval 0.75 to 0.85. Synonymous variants: 387 observed, 358.13 expected, observed/expected ratio (o/e) 1.08, 90% interval 0.99 to 1.17.
Homologues: Orthologues: chimpanzee USP49 (99% identical), macaque USP49 (98% identical), rabbit USP49 (93% identical), dog USP49 (92% identical), pig USP49 (92% identical), mouse Usp49 (90% identical), rat Usp49 (89% identical), guinea pig USP49 (85% identical), zebrafish usp49 (60% identical). Paralogues in human: USP44 (60% identical), USP3 (26% identical), USP20 (25% identical), USP33 (24% identical), USP19 (19% identical), USP4 (18% identical), USP51 (18% identical), USP32 (18% identical), USP15 (18% identical), USP31 (18% identical), USP37 (18% identical), USP22 (18% identical), and 59 more.